SKP2 (S-phase kinase associated protein 2)
Diseases named in the same sentence as SKP2 in open-access papers (continued):
Sharing a sentence is not in itself a finding about the gene and the disease.
tumor (continued). "Even though there are some differences between our patients and the TCGA cohort patients, BIRC5 and SKP2 were still both overexpressed in HCC tissues compared with tumor-adjacent tissues in our TMA cohort." (PMID 37679418, 2023). "To this end, we depleted SKP2 expression for 48 h in the FN-RMS cell lines RD and JR1 (both with mutated p5324), derived from recurrent and metastatic tumor samples, respectively." (PMID 38102140, 2023). "Knockdown of Skp2 inhibited viability, anchorage-independent growth, and in vivo tumor development of NSCLC cells." (PMID 37532777, 2023). "SKP2 genetic depletion arrests cell proliferation, inhibits stemness and restores myogenic differentiation in vitro and in vivo preventing tumor growth." (PMID 38102140, 2023). "In other words, in these neoplasm cells, those with low SKP2 expression tend to be depleted, suggesting SKP2 can promote the development of these neoplasms." (PMID 37308972, 2023). "The prognosis significance of SKP2 in individuals with neoplasm was evaluated through univariate Cox regression analysis and Kaplan-Meier curves." (PMID 37308972, 2023). "This study also suggested the potential direction of SKP2 in tumor-related research and the drugs targeting this molecule." (PMID 37308972, 2023). "We first examined the protein level of Skp2 by Western blotting in immortalized non-tumor cell HBE and MRC5 and a panel of human NSCLC cell lines." (PMID 37532777, 2023). "It has been reported that Skp2 is involved in the regulation of cell cycle, cell apoptosis and senescence, while it promotes tumor progression and radio/chemotherapy resistance." (PMID 37779163, 2023). "Dioscin is a novel inhibitor of SKP2 that promotes ubiquitin-dependent degradation of SKP2 that leads to suppressed tumor growth in vivo." (PMID 37176148, 2023). "High expression of SKP2 was widely observed in various human tumors, indicating the close correlation between tumor progression and SKP261–63." (PMID 37679418, 2023). "Currently, SKP2 is not only an independent prognostic factor for HCC but also a new target for anti-tumor drugs and gene therapy." (PMID 37679418, 2023). "SKP2 recognized tumor suppressor substrates and was targeted for ubiquitination and degradation by the proteasome via the E3 ligase SKP1-Cullin1-F-box." (PMID 37915040, 2023). "Since been reported to regulate cell cycle, promoting cell proliferation via p27, Skp2 was discovered to have various other functions in tumor pathological processes, including apoptosis, DNA repair, tumor metastasis, and senescence." (PMID 37089937, 2023). "Skp2 was a rate-limiting factor of the degradation of p27 protein, and the Skp2-p27 axis controlled S phase entry, tumor stemness as well." (PMID 37089937, 2023). "Treatment of xenograft mice with the SKP2 inhibitor SZL P1‐41 decreased tumor proliferation, SKP2:FOXA1 ratios, and colocalization." (PMID 37491794, 2023). "Gene set enrichment analysis was used to identify essential signaling pathways of SKP2 in human neoplasms." (PMID 37308972, 2023). "Mechanistic insight shows that Moesin prevents FBXW2-SKP2 interaction and attenuates FBXW2-mediated SKP2 polyubiquitination and degradation ultimately leading to tumor growth." (PMID 37736741, 2023). "SKP2 expression made it feasible to distinguish neoplasm and control tissues of 21 neoplasms (sensitivity = 0.79, specificity = 0.87, area under the curve = 0.90), implying its potential in screening a series of neoplasms." (PMID 37308972, 2023). "SKP2 expression made it feasible to distinguish the neoplasm and control tissues of 21 neoplasms, implying its potential in screening a series of neoplasms." (PMID 37308972, 2023). "SKP2 knockdown strongly delayed the appearance of tumor masses and strikingly reduced tumor size and weight compared with tumors from scrambled shRNA cells in the same mice." (PMID 38102140, 2023).
tumor (continued). "The results showed that increased SKP2 expression tended to be observed in advanced AJCC stages for certain neoplasms (p < 0.05)." (PMID 37308972, 2023). "The study identified the potential of SKP2 as a marker for the treatment and identification of these neoplasms." (PMID 37308972, 2023). "In CRC tumors, combined menin inhibition and iEGFR treatment induces CRC cell apoptosis in vitro and inhibits CRC tumor xenograft growth in vivo, as iEGFR treatment induces calcium release to repress promoting SKP2 transcription by menin." (PMID 37089937, 2023). "First, we found that FOXO3A was less expressed in ccRCC tumor tissues and cell lines, and negatively correlated with Aur-A and SKP2 expression." (PMID 35831273, 2022). "Skp2 modulation, and the loss of its substrates p27 and Mcm6, and the E2f family are clinical markers for a poor outcome in CRC, its malignancy, and CRC tumor growth." (PMID 35457963, 2022). "Xenograft tumors derived from Skp2-null HCT116 cells that were treated with irradiation exhibited reduced tumor growth, tumor mass, and tumor cell proliferation." (PMID 35301297, 2022). "Hinokitiol has also been shown to inhibit tumor cell proliferation, in part, by G1 cell cycle arrest characterized by downregulated pRb and Skp2 ubiquitin ligase, and an impaired Cdk2 kinase activity." (PMID 35399709, 2022). "Simultaneously targeting both SKP2 and Aur-A showed a synergistic tumor growth inhibition in vivo and in vitro of ccRCC models, suggesting a potential new therapeutic strategy for ccRCC." (PMID 35831273, 2022). "We also collected four pairs of clinical samples (including tumor tissues and adjacent normal tissues) and five ccRCC cell lines to detect the protein level of SKP2, and further confirmed that SKP2 was highly expressed in ccRCC tumor tissues and cells." (PMID 35831273, 2022). "This gene signature is presumably highly related to the levels of SKP2 as well as its downstream tumor suppressor targets such as p27." (PMID 35169199, 2022). "The results showed that Skp2 is significantly more highly expressed in CRC tumor tissue than in adjacent non-tumor tissues." (PMID 35301297, 2022). "Here, we reported that SKP2 expression was prominently increased both in ccRCC tumor tissues and cells, and the high expression of SKP2 predicted a worse survival of ccRCC." (PMID 35831273, 2022). "The combination of Aur-A inhibitor MLN8237 and SKP2 inhibitor SZL P1-41 showed a synergistic tumor growth inhibition in vivo and in vitro of ccRCC models." (PMID 35831273, 2022). "Targeting the Skp2-Mcl-1 axis is a promising anti-tumor strategy to overcome radioresistance in CRC." (PMID 35301297, 2022). "As many of SKP2’s targets halt the cell-cycle progression and are therefore tumor suppressors, SKP2 has an oncogenic role in many cancers." (PMID 35169199, 2022). "The accumulation of SKP2 subsequently leads to the degradation of tumor suppressors and apoptosis-inducing substrates, such as p21, p27, p130, and FOXO1, to promote tumor cell proliferation, growth, and survival." (PMID 35414786, 2022). "Inhibitors of SKP2 with anti-tumor properties include several natural products and recently identified small molecule compounds." (PMID 34178666, 2021). "The CD34-marked tumor vessels in circCRIM1-overexpressing tumors were larger and more abundant, while SKP2 expression was obviously higher." (PMID 34869393, 2021). "As a bona fide substrate, the degradation of P27 in nucleus emphasizes SKP2 as a tumor driver, by which it facilitates cell cycle entry and proliferation in many cancers." (PMID 34433808, 2021). "The p21 and p27 are downstream proteins of Skp2 and are vital for proliferation, survival, and periodic distribution of tumor cells." (PMID 34702937, 2021). "As we previously discussed, nobiletin inhibited tumor progression by regulating the SKP2-p21/p27-CDK2 axis, and the insensitivity of the CDK4/6 inhibitor, palbociclib, was associated with higher SKP2 levels in RCC cells." (PMID 33628597, 2021).
tumor (continued). "Recently, a number of studies have reported that miR-340 plays a critical role in tumor initiation and progression, by targeting multiple oncogenes such as SKP2, FHL2, c-Met, and ROCK1." (PMID 33390846, 2021). "When phosphorylated at threonine on p27 protein 188 sites, Skp2 interacts with Cks1 and leads to p27 degradation through the ubiquitin–proteasome system which promotes tumor proliferation and migration." (PMID 34702937, 2021). "Consistent with in vitro data, tumor levels of Skp2 were reduced by EPI-7170, combination therapy, and to a modest extent by ATRA." (PMID 33753863, 2021). "Recently, two groups independently demonstrated that SETDB1-mediated methylation of Akt at K64 or K140/K42 crosstalks with PI3K and TRAF6/Skp2 to promote Akt activation and tumor growth." (PMID 33670113, 2021). "Nobiletin downregulated the SKP2-p21/p27-CDK2 axis to inhibit tumor progression and showed synergistic tumor inhibition effects with the CDK4/6 inhibitor, palbociclib, on RCC, which indicates a potential new therapeutic strategy." (PMID 33628597, 2021). "Skp2 belongs to the F-box protein family that has the potential to act as one of anti-tumor therapeutic targets and prognostic biomarkers via the proteolytic pathway." (PMID 34572430, 2021). "Future studies on the role of Skp2 in tumor immunity can help clarify the potential mechanism of tumor immune escape and the antitumor effect of Skp2 inhibitors." (PMID 34943817, 2021). "Skp2 antagonizes the tumor suppression function of FOXO1 by promoting ubiquitination and degradation of the FOXO1 protein." (PMID 34068643, 2021). "The miR-30 family targeted Skp2 in the premetastatic phase in the lungs of B16 tumor-bearing mice, leading to inhibition of pulmonary vascular hyperpermeability." (PMID 33621206, 2021). "Nobiletin downregulated the SKP2-p21/p27-CDK2 axis to inhibit tumor growth and progression in RCC cells." (PMID 33628597, 2021). "We found that 10 of 11 genes (all except Prosalpha7) identified in our pipeline effectively inhibited proliferation of tumor cells, as did the positive controls Skp2 and E2F." (PMID 33591981, 2021). "Probably because of its proteolysis effects on its substrates like p21, p27, PDCD4 and FOXO1, a large part of which are tumor suppressors, SKP2 mainly play oncogenic functions." (PMID 32226545, 2020). "In the xenograft mice model, both of the tumor size and weight were reduced upon Skp2 knockdown (***p < 0.001)." (PMID 32165861, 2020). "Skp2 has been shown to be highly expressed in various types of tumors and play important roles in tumor development, especially in cell proliferation and drug sensitivity." (PMID 32165861, 2020). "In non–small‐cell lung cancer cells, SIRT2 inhibits tumour growth by impairing Skp2‐mediated p27 degradation." (PMID 32697380, 2020). "In accordance with our above results, Western blot analysis revealed that CCNA2, MCM7 and SKP2 expression were decreased in the MTHFD2 knockdown tumour tissues compared with shCtrl tumour tissues." (PMID 31778025, 2020). "The robust antileukemic effect of SKP2 deletion on some mice raises the possibility that SKP2 exerts tumor suppressive effects also through additional mechanisms other than cell cycle." (PMID 31772299, 2020). "In contrast, a new oncogenic isoform of TRβ2, TRβ2-46, increases expression and stability of the SKP2 protein, which counteracts the TRβ1 tumor-suppressive function and thus promotes the proliferation of retinoblastoma cells." (PMID 32824373, 2020). "Treatment of a PC-3-Pa cell-implanted xenograft mouse model with 3 or 10mg/kg LJ-2618 effectively inhibits tumor growth by enhancing SKP2 degradation and by inducing p27 expression in the tumor tissues." (PMID 30669516, 2019). "The data indicated that ATO exerts its tumor-suppressive function in part via upregulation of miR-330-5p and subsequent inhibition of Skp2 in PC cells." (PMID 30847385, 2019).
tumor (continued). "Previous studies have used various inhibitors of Skp2 to retard the growth of tumor cells or induce apoptosis." (PMID 31038581, 2019). "Our study showed PDCD4 is a novel ubiquitination substrate of SKP2, which helps to clarify SKP2 tumor promotion and DNA damage response action." (PMID 30760284, 2019). "Previous research together with our results imply that SKP2 is potential radiotherapy or anti-tumor drug sensitization target." (PMID 30760284, 2019). "We found 5 target gene candidates (Skp2, Psme3, Pik3cd, Klf4, and Hoxb5) that were consistently predicted by the three software and involved in tumor-related signaling pathway." (PMID 30967999, 2019). "We found that nuclear expression of Skp2 was increased in patients with PCa compared to those with benign hyperplasia, and correlated with high Gleason score in PCa patients." (PMID 30952903, 2019). "In our work, we showed that Skp2 expression was increased in cancerous prostate tissue compared to benign prostate tissue, specifically in tumours with a high Gleason score (≥7)." (PMID 30952903, 2019). "Previous studies demonstrated that overexpression of SKP2 induced tumor formation while ablation of SKP2 impaired tumorigenesis in xenograft models and genetically engineered mouse models." (PMID 29891922, 2018). "For example, a specific SKP2 inhibitor that selectively suppresses the CRL1 E3 ligase activity was reported to exhibit anticancer activity against human tumor xenografts in mice." (PMID 29594129, 2018). "In agreement with previous results, the tumor immunohistochemical staining data indicates that the mTORC1 pathway regulates Skp2 expression through phosphorylation of Skp2." (PMID 28446188, 2017). "Our results showed that simvastatin inhibited tumor growth and that the expression patterns of p21, p27, Skp2, AMPK and STAT3 were similar to those of the in vitro study." (PMID 28230855, 2017). "In works of Oncomine data base, the expression of Skp2 at mRNA level in tumor samples was significantly higher than in counterpart normal lung tissues." (PMID 27835873, 2017). "High expression of Skp2 is clinically correlated with low expression of p27, a tumor suppressor and critical regulator of cell cycle." (PMID 28036296, 2017). "Immunohistochemistry analysis results indicated that YF-18 induced down-regulation of Skp2 in tumor samples." (PMID 28036296, 2017). "When cells were arrested in response to serum starvation, the level of tumour suppressive FBXW2 is high to keep SKP2 level low and p21/p27 high." (PMID 28090088, 2017). "Consistently, we found that simvastatin also increased p21 and p27 expression in tumor sections by reducing Skp2 expression and inducing AMPK activation and STAT3 suppression in the same tumor tissues." (PMID 28230855, 2017). "Among the 10 amplification-based oncogenes, we identified that six genes (MDM2, MYC, MYCL, MYCN, NKX2-1, and SKP2) were amplified and overexpressed in ≥10 tumor samples." (PMID 28377632, 2017). "Here, the authors identify an axis of F-box proteins β-TrCP1-FBXW2-SKP2 where FBXW2 is a substrate of β-TrCP1 but mediates the degradation of SKP2, thus acting as a tumour suppressor." (PMID 28090088, 2017). "Testosterone-mediated tumor senescence paralleled with decreased SKp2 and increased p21 and p27 expression." (PMID 29371946, 2017). "Reduced levels of NICD1 and Notch1 target genes, such as Skp2, c-Myc and Hes1, confirmed that PF-03084014 efficiently reached the target in Ptenpc−/− tumours." (PMID 27941799, 2016). "Using genome-wide array comparative genomic hybridization, we previously profiled deoxyribonucleic acid (DNA) copy number alterations and identified SKP2 gene amplification confers tumor aggressiveness in myxofibrosarcoma." (PMID 27317767, 2016).
tumor (continued). "More importantly, we confirmed that rottlerin exerts its anti-tumor function via inactivation of Skp2." (PMID 27582552, 2016). "As observed in Ptenpc−/− mice, treatment with PF-03084014 increased p27 levels and decreased Skp2 protein levels also in Ptenpc−/−; Trp53pc−/− tumours." (PMID 27941799, 2016). "Human colorectal tumour arrays show higher percentage of SKP2 positive samples and lower percentage of FZR1 and p27KIP1 positive samples and high FZR1 expression was associated with tumours showing lower grade histology." (PMID 27402801, 2016). "Tumours were excised at the end of the study and the effect of compound treatment assessed on the pharmacodynamics markers, neddylated Cul1 and Skp2." (PMID 27774986, 2016). "In line with the anti-tumour efficacy, Cul1 deneddylation was inhibited and Skp2 levels were reduced in the tumours of the treated mice but not in those from vehicle controls." (PMID 27774986, 2016). "For instance, it has been shown that SKP2 cooperates with H-RasG12V to trigger both cellular transformation in primary rodent fibroblasts and tumor formation in nude mice." (PMID 25537506, 2015). "Skp2 overexpression in PCa cells stimulates PCa cell proliferation and increases the tumorigenesis in xenograft tumor model." (PMID 25788262, 2015). "In the present study, the roles of the c-Myc/Skp2/Fbw7 and HDAC1/2 pathways, which are associated with tumor progression, on the anticancer effects of AMP in the A549 NSCLC line were investigated." (PMID 25333250, 2015). "In SKP2/N-RasV12 and SKP2/myr-AKT1 mice, the molecular substrates of SKP2 in mediating its oncogenic activity presumably differ from the canonical targets of SKP2 previously identified in many tumor types." (PMID 25537506, 2015). "Noticeably, recently developed soluble inhibitors of SKP2 have shown encouraging anti-neoplastic effects in various tumor types." (PMID 25537506, 2015). "The average tumor mass of Ptenpc−/−; Trp53pc−/−; Skp2−/− mice reduced 2.68-fold as compared to that of Ptenpc−/−; Trp53pc−/− mice (P < 0.001, N = 12 mice)." (PMID 25596733, 2015). "Based on this body of evidence, it seems plausible that SKP2 acts as a tumor initiator and/or promoter depending on the tissue type and the model used." (PMID 25537506, 2015). "Altogether, the present data indicate that combined overexpression of SKP2 and N-Ras is able to induce tumor development in the mouse liver." (PMID 25537506, 2015). "In sum, these findings demonstrate that Wnt7a is a novel inducer of tumor-suppressive cellular senescence via the modulation of the expression of SKP2-mediated alternate senescence pathway." (PMID 25728679, 2015). "We further validated that curcumin exerts its anti-tumor function partly through down-regulation of Skp2." (PMID 26046466, 2015). "Taken together, curcumin exerts its anti-tumor activity through down-regulation of Skp2 signaling pathway." (PMID 26046466, 2015). "Positive SKP2 and cyclin E staining was present in the nucleus of tumor cells, whereas positive stathmin staining was detected in the cytoplasm." (PMID 25106448, 2014). "Gstaiger showed that cotransfection of SKP2 and H-Ras significantly increased tumor formation in an animal model." (PMID 25106448, 2014). "The level of SKP2 protein upregulation, which induces uncontrolled cell proliferation and tumor progression, was also reduced by ezetimibe." (PMID 25310357, 2014). "Validation of compound ♯25 showed that it effectively inhibits Skp1/Skp2 interaction and Skp2 mediated p27 ubiquitination as well as tumour growth in a mouse xenograft model." (PMID 25237759, 2014). "Recent studies on the clinical samples from Taiwan and South China showed that Skp2 was overexpressed in 80% NPC tumor and the expression was correlated with poor prognosis." (PMID 24156782, 2013). "It is known that the c-Myc/Skp2/Fbw7α and HDAC1/HDAC2 pathways, are associated with tumor progression." (PMID 24265759, 2013).